FAM20A (FAM20A golgi associated secretory pathway pseudokinase)
Description:
Pseudokinase that acts as an allosteric activator of the Golgi serine/threonine protein kinase FAM20C and is involved in biomineralization of teeth. Forms a complex with FAM20C and increases the ability of FAM20C to phosphorylate the proteins that form the 'matrix' that guides the deposition of the enamel minerals.
Synonyms: DKFZp434F2322; AI1G; AIGFS; FP2747
Tractability: Small molecule: a structure with a bound ligand is known. Antibody: UniProt places it where antibodies can reach, with medium confidence; UniProt predicts a signal peptide or a membrane-spanning region; its Gene Ontology location is reachable by antibodies, with medium confidence.
Gene: Protein-coding gene on chromosome 17 (68,535,113 to 68,601,384, reverse strand). Ensembl gene ENSG00000108950.
Subcellular location: Secreted; Golgi apparatus; Endoplasmic reticulum
Pathways (Reactome):
Metabolism of proteins: Post-translational protein phosphorylation; Regulation of Insulin-like Growth Factor (IGF) transport and uptake by Insulin-like Growth Factor Binding Proteins (IGFBPs)
Gene Ontology:
Molecular function: protein binding; protein serine/threonine kinase activator activity; protein serine/threonine kinase activity; phosphotransferase activity, alcohol group as acceptor
Biological process: biomineral tissue development; calcium ion homeostasis; enamel mineralization; positive regulation of protein phosphorylation; tooth eruption
Cellular component: extracellular exosome; extracellular region; Golgi apparatus; cytoplasm; endoplasmic reticulum
Genetic constraint (gnomAD): Loss-of-function variants: 40 observed, 47 expected, observed/expected ratio (o/e) 0.85, 90% interval 0.66 to 1.11. The upper end of that interval is the gene's LOEUF score, 1.11, which puts it in group 4 of 6, group 1 being the genes least tolerant of losing a copy. Missense variants: 738 observed, 689.29 expected, observed/expected ratio (o/e) 1.07, 90% interval 1.01 to 1.14. Synonymous variants: 303 observed, 282.54 expected, observed/expected ratio (o/e) 1.07, 90% interval 0.98 to 1.18.
Homologues: Orthologues: chimpanzee FAM20A (99% identical), macaque FAM20A (96% identical), pig FAM20A (90% identical), rabbit FAM20A (89% identical), dog FAM20A (88% identical), guinea pig FAM20A (87% identical), mouse Fam20a (86% identical), rat Fam20a (85% identical), tropical clawed frog fam20a (58% identical), zebrafish fam20a (58% identical), Drosophila melanogaster CG31145 (36% identical), Caenorhabditis elegans famk-1 (30% identical). Paralogues in human: FAM20C (45% identical), FAM20B (27% identical).
Diseases named in the same sentence as FAM20A in open-access papers:
FAM20A is named in the same sentence as 48 diseases in open-access papers, as found by Europe PMC text mining. Sharing a sentence is not in itself a finding about the gene and the disease. The quoted sentences say what the papers report.
amelogenesis imperfecta (20 papers, 2012 to 2025). Amelogenesis imperfecta (AI) represents a group of developmental conditions affecting the structure and clinical appearance of the enamel of all or nearly all the teeth in a more or less equal manner, and which may be associated with morphologic or biochemical changes elsewhere in the body. "Nonetheless, the physiological importance of the FAM20A-FAM20C complex is clearly demonstrated by the fact that genetic ablation of FAM20A leads to Amelogenesis Imperfecta, that phenocopy mutations in FAM20C itself." (PMID 41301500, 2025). "The case initially presented as congenital adrenal hyperplasia and amelogenesis imperfecta, but further genetic analysis revealed the involvement of AIGFS due to a mutation in the FAM20A gene." (PMID 38465125, 2024). "Mutations in FAM20A have been demonstrated to cause amelogenesis imperfecta and enamel renal syndrome." (PMID 34020624, 2021). "Variations in the gene encoding Fam20A result in amelogenesis imperfecta (AI), nephrocalcinosis (NC), and ectopic calcification (EC)." (PMID 33759783, 2021). "FAM20A knockout mice have biomineralization defects, and mutations in FAM20A have been found to be associated with amelogenesis imperfecta subsequently." (PMID 31133012, 2019). "Background and objective:FAM20A gene mutations result in enamel renal syndrome (ERS) associated with amelogenesis imperfecta (AI), nephrocalcinosis, gingival fibromatosis, and impaired tooth eruption." (PMID 28515694, 2017). "Mutations in FAM20A cause tooth enamel defects known as Amelogenesis Imperfecta (AI) and renal calcification." (PMID 28432788, 2017). "Non-sense or missense mutations in the FAM20A gene were identified that are associated with an autosomal recessive type of Amelogenesis Imperfecta (AI), resulting in premature termination or amino acid changes of the peptides (OMIM#614253)." (PMID 27292199, 2016). "Among these genes, FAM20A mutations are associated with Amelogenesis Imperfecta (AI) with gingival hyperplasia and nephrocalcinosis, while FAM20C mutations cause Raine syndrome, exhibiting bone and craniofacial/dental abnormalities." (PMID 27292199, 2016). "Recently, disease-causing mutations in the FAM20A gene were identified, in families with an autosomal recessive syndrome associating amelogenesis imperfecta and gingival fibromatosis." (PMID 25636655, 2015). "Biallelic FAM20A mutations cause two conditions where Amelogenesis Imperfecta (AI) is the presenting feature: Amelogenesis Imperfecta and Gingival Fibromatosis Syndrome; and Enamel Renal Syndrome." (PMID 26740946, 2015). "Our finding confirms that the mutations of FAM20A gene are causative for amelogenesis imperfecta and gingival fibromatosis and underlines the recurrent character of the c.34_35delCT in two different ethnic groups." (PMID 25636655, 2015). "Whole-Exome sequencing identifies FAM20A mutations as a cause of amelogenesis imperfecta and gingival hyperplasia syndrome." (PMID 24927635, 2014). "Recently, mutations in FAM20A were reported to cause amelogenesis imperfecta and gingival fibromatosis syndrome (AIGFS), which closely resembles ERS except for the renal calcifications." (PMID 23468644, 2013). "This au-tosomal recessive disorder, also known as enamel renal syndrome, of FAM20A causes nephrocalcinosis and amelogenesis imperfecta." (PMID 23434854, 2012). "Consequently, FAM20A has garnered less research focus, though some studies have linked its variants to amelogenesis imperfecta (AI), nephrocalcinosis (NC), and ectopic calcification (EC), highlighting its critical role in several diseases." (PMID 38983866, 2024). "FAM20A golgi is associated with the secretory pathway pseudokinase (FAM20A), which encodes a protein that might function in haematopoiesis and is associated with amelogenesis imperfecta and gingival hyperplasia syndrome." (PMID 32792959, 2020). "Mutations in human FAM20A cause amelogenesis imperfecta, gingival fibromatosis and kidney problems." (PMID 27281036, 2016).
amelogenesis imperfecta (continued). "The function of FAM20A is unknown, but defects in the FAM20A gene have recently been shown to cause dental enamel defects along with enlarged gingiva (amelogenesis imperfecta and gingival fibromatosis syndrome or AIGFS; OMIM #614253)." (PMID 23468644, 2013). "It is reported in some literature that FAM20A participates in the regulation of FAM20C activity by crystal structure analysis, and mutations in FAM20A also cause amelogenesis imperfecta, enamel–renal syndrome, and gingival fibromatosis syndrome." (PMID 36825005, 2023). "Dysfunction of FAM20A leads to a unique syndrome recognized as renal enamel syndrome or amelogenesis imperfecta with gingival fibromatosis." (PMID 36767768, 2023). "These unusual dental changes are rare in patients with non-syndromic amelogenesis imperfecta, but are hallmark features of Enamel-Renal Syndrome (ERS) and were observed in the teeth from our probands with FAM20A mutations and nephrocalcinosis." (PMID 23468644, 2013). "However, considering that FAM20A is expressed in the normal brain, individuals with amelogenesis imperfecta and gingival hyperplasia syndrome with a deficiency of FAM20A have not been reported to present neural impairments." (PMID 37240249, 2023).
enamel renal syndrome (13 papers, 2012 to 2025). "Disease-causative variants in FAM20A lead to enamel renal syndrome (ERS), a rare hereditary disorder combining AI, gingival fibrosis and nephrocalcinosis." (PMID 38664418, 2024). "While mutations in AMBN and ACP4 cause non-syndromic autosomal recessive hypoplastic AI, mutations in FAM20A cause syndromic autosomal recessive hypoplastic AI (enamel-renal syndrome, OMIM#204690)." (PMID 33652941, 2021). "FAM20A is known to be involved in biomineralisation of teeth and mutations in this gene have previously been linked to dental defects and enamel renal syndrome." (PMID 28922377, 2017). "FAM20A mutations were also identified as the cause of “Amelogenesis Imperfecta and Gingival Fibromatosis Syndrome” (AIGFS, MIM#614253)." (PMID 24927635, 2014). "Enamel renal syndrome is hypothesized to be associated with mutations in the FAM20A gene, which results in aberrant mineralization of the gingiva, dental follicles, kidneys, and lungs." (PMID 39583392, 2024). "Amelogenesis imperfecta type 1G (AI1G), also known as Enamel-Renal-Gingival Syndrome (ERGS), is an autosomal recessive disorder caused by variants in FAM20A, encoding a Golgi apparatus protein crucial for protein processing and secretion." (PMID 40693438, 2025).
nephrocalcinosis (10 papers, 2012 to 2026). Nephrocalcinosis is a disorder that occurs when too much calcium is deposited in the kidneys. "This is caused by recessive FAM20A mutations, characterized by hypoplastic AI, pulp stones, delayed or failed eruptions of secondary dentition, gingival overgrowth, and nephrocalcinosis." (PMID 35327733, 2022). "Variants of FAM20A causes enamel‐renal syndrome which is characterized by defective mineralization of dental enamel and nephrocalcinosis." (PMID 34957696, 2021). "WDR72 has also been identified as causative for distal renal tubular acidosis, which in turn is associated with nephrocalcinosis and thus shares important parallels with FAM20A." (PMID 34957696, 2021). "More recently, FAM20A gene mutations have been identified in hypoplastic AI associated with gingival fibromatosis and with nephrocalcinosis." (PMID 28515694, 2017). "We speculate that all individuals with biallelic FAM20A mutations will eventually show nephrocalcinosis." (PMID 23434854, 2012). "Among our patients, patients 1 and 3 exhibited mild-to-moderate nephrocalcinosis with ectopic calcifications, consistent with classic FAM20A-related ERS." (PMID 41427162, 2025). "For example, mutations in six of the amelogenesis imperfecta-associated genes (CLDN16, CLDN19, FAM20A, KCNJ1, SLC4A1, and WDR72) are associated with nephrocalcinosis, hypercalciuria, and renal failure." (PMID 33672174, 2021). "ERS is characterized by defective mineralization of dental enamel and nephrocalcinosis suggesting that FAM20A is an extracellular matrix protein, dysfunction of which causes calcification of the secretory epithelial tissues." (PMID 34957696, 2021). "The common phenotype observed in mouse and man suggests that FAM20A plays a role in enamel secretion and maturation stages, although its distinct roles in amelogenesis and nephrocalcinosis remain to be discovered." (PMID 24927635, 2014). "Only further studies can show if defects in other gene(s) can cause this pattern of malformations and if FAM20A defects were not previously associated with nephrocalcinosis due to a lack of penetrance, subclinical presentation, or delayed onset." (PMID 23468644, 2013). "Additional support for the association of nephrocalcinosis and the absence of FAM20A comes from recent analyses of Fam20a null mice, which discovered that “two-thirds of Fam20a−/− mice had small kidneys with pitted surfaces, which showed widespread calcification...”." (PMID 23468644, 2013).
gingival fibromatosis (6 papers, 2015 to 2025). "Building upon our previous findings demonstrating the impact of FAM20A insufficiency on deciduous dental pulp cells, this study investigated the molecular mechanisms underlying gingival fibromatosis in AI1G." (PMID 40693438, 2025).
gingival hyperplasia (4 papers, 2013 to 2016). "Mutations in human FAM20A were shown to cause amelogenesis imperfecta and gingival hyperplasia." (PMID 25749104, 2015).
Raine syndrome (3 papers, 2015 to 2020). "Since the localization of FAM20A was similar to that of FAM20C in tooth, and clinical phenotypes of AI patients with FAM20A mutation partially overlap with those of Raine syndrome patients, we investigated the association of FAM20A with FAM20C." (PMID 27292199, 2016).
gingival overgrowth (2 papers, 2020 to 2022). Excessive growth of the gingiva either by an increase in the size of the constituent cells (gingival hypertrophy) or by an increase in their number (gingival hyperplasia). "Its function in this site is unclear, but Keratin-14:Cre driven epithelial ablation of FAM20A is sufficient to induce gingival overgrowth in mice." (PMID 33425910, 2020).
glioma (2 papers, 2022 to 2023). A benign or malignant brain and spinal cord tumor that arises from glial cells (astrocytes, oligodendrocytes, ependymal cells). "FAM20A may play a more complex role in gliomas, as correlations between FAM20A genes and low-grade gliomas have been found." (PMID 37538797, 2023). "Correlations between the ABCC3, COL6A2 and FAM20A genes and low-grade glioma suggested that these genes might play more complex roles in gliomas." (PMID 35456975, 2022).
hypophosphatemia (2 papers, 2016 to 2026). Lower than normal levels of phosphates in the circulating blood. "The identification of elevated FGF-23 levels in FAM20A-related ERS with severe nephrolithiasis and hypophosphatemia raises the question of the interest of burosumab as targeted therapy." (PMID 41645214, 2026).
lung squamous cell carcinoma (2 papers, 2024). "In addition, recent research suggests that two members of the sequence similarity family, FAM20A and FAM83A, have potential clinical applications in lung squamous cell carcinoma." (PMID 39544292, 2024).
aortic valve calcification (1 paper, 2021). "The expression of SPP1, TNC, SCG2, FAM20A, and CD52 was all significantly up-regulated in calcific aortic valve disease." (PMID 34020624, 2021). "However, the role of FAM20A in aortic valve calcification remains unclear." (PMID 34020624, 2021).
atherosclerosis (1 paper, 2024). A disease characterized by the build-up of fatty material and calcium deposition in the arterial wall resulting in partial or complete occlusion of the arterial lumen. "Firstly, heatmap analysis of the three differential genes including MYBL1, ARHGAP30 and FAM20A were performed and found that MYBL1 had the highest expression in early atherosclerotic tissues and the lowest expression in advanced atherosclerosis, while FAM20A and ARHGAP30 had the opposite trend." (PMID 38797732, 2024).
calcification (1 paper, 2020). Process by which organic tissue becomes hardened by the physiologic deposit of calcium salts. "Nevertheless, the results presented here strongly support the idea that, like in other soft tissues, gingival calcification caused by FAM20A dysfunction is an organized biomineralization process involving chondro/osteogenic trans-differentiation of fibroblastic cells." (PMID 33425910, 2020).
chronic kidney disease (1 paper, 2020). Impairment of the renal function secondary to chronic kidney damage persisting for three or more months. "It is unclear how FAM20A may cause hyperphosphatemia, a major risk factor for chronic kidney disease, but our data are compatible with ERS-associated renal dysfunction or failure." (PMID 33425910, 2020).
diabetes (1 paper, 2021). "Microarray analysis of the PBMC dataset (Cohort 1), identified FcER1, TRPC3, SNX20, FAM20A, and SLC12A7 as genes showing increased expression with the severity of diabetes." (PMID 34925339, 2021).
embryonal carcinoma (1 paper, 2022). A non-seminomatous malignant germ cell tumor characterized by the presence of large germ cells with abundant cytoplasm resembling epithelial cells, geographic necrosis, high mitotic activity, and pseudoglandular and pseudopapillary structures formation. "Consistent with this possibility, it has been reported that FAM20A was downregulated by 3.8-fold when a bulk of LTR5_Hs copies were altered to have a repressive modification in human embryonal carcinoma cells, using the CRISPRi system." (PMID 36219870, 2022).
fibromatosis (1 paper, 2021). A poorly circumscribed neoplasm arising from the soft tissues. "How mutations in FAM20A may modify the gingival connective tissue homeostasis and cause fibromatosis is currently unknown." (PMID 34777248, 2021).
Fraser syndrome (1 paper, 2023). Fraser syndrome is a rare clinical entity including as main characteristics cryptophthalmos and syndactyly. "In addition, severe kidney disease can also sometimes be associated with congenital/hereditary factors as in the case of Fraser Syndrome, FAM20A mutation, or X chromosome-related hypophosphatemia." (PMID 36767768, 2023).
osteoarthritis (1 paper, 2015). A noninflammatory degenerative joint disease occurring chiefly in older persons, characterized by degeneration of the articular cartilage, hypertrophy of bone at the margins and changes in the synovial membrane. "Lastly, we demonstrated the biological significance of Fam20a expression in chondrocytes by evaluating osteoarthritis-related gene expression of primary articular chondrocytes." (PMID 25749104, 2015).
osteosarcoma (1 paper, 2015). A usually aggressive malignant bone-forming mesenchymal neoplasm, predominantly affecting adolescents and young adults. "Furthermore, ectopic expression of Fam20A in the human osteosarcoma cell line U2OS, which produces Fam20C, but not Fam20A, significantly increased phosphorylation of V5-tagged OPN, ENAM and AMBN, without altering Fam20C expression levels." (PMID 25789606, 2015).
osteosclerosis (1 paper, 2020). Abnormally high bone density. "Surprisingly, ERS patients do not suffer from constitutional bone diseases such as osteosclerosis indicating that FAM20A does not participate predominantly in the secretion of FAM20C in the developing bone." (PMID 33425910, 2020).
papillary thyroid carcinoma (1 paper, 2020). "There are few reports on the relationship between FAM20A and cancer, and our experiment found that FAM20A is more highly expressed in papillary thyroid carcinoma than in other cancers." (PMID 32766727, 2020).
periodontitis (1 paper, 2020). An acute or chronic inflammatory process that affects the tissues that surround and support the teeth. "Among the FAM20 family, it has been reported that periodontitis may be a part of clinical phenotypic spectrum in FAM20A mutations." (PMID 33051588, 2020).